ETV5 (ETS variant transcription factor 5)
Diseases named in the same sentence as ETV5 in open-access papers (continued):
Sharing a sentence is not in itself a finding about the gene and the disease.
bladder cancer (4 papers, 2019 to 2025). "Firstly, we confirmed that mutant FGFR3 causes an increase in ETV5 expression in bladder cancer cells by using the two cell lines with the commonest FGFR3 mutation, 97-7 and UMUC14." (PMID 30952872, 2019). "We also demonstrate that ETV5 is a key downstream mediator of the oncogenic effects of mutant FGFR3, as its knockdown in FGFR3-mutant bladder cancer cell lines is associated with reduced proliferation and anchorage-independent growth." (PMID 30952872, 2019). "Overall therefore, our results show that ETV5 confers a proliferative advantage to bladder cancer cells." (PMID 30952872, 2019). "Our data show that ETV5 is important in maintaining the malignant phenotype of bladder cancer cells, and that its knockdown can recapitulate some of the phenotypic effects of FGFR3 knockdown in UC cells, such as decreased cell proliferation and reduced anchorage independent growth." (PMID 30952872, 2019). "In conclusion, this is the first comprehensive investigation of the role of ETV5 in bladder cancer." (PMID 30952872, 2019). "Notably, ETV5 was one of the genes significantly downregulated after FGFR3 silencing in the bladder cancer cell line RT11251, or after treatment of cancer cell lines with the FGFR inhibitor AZD454752, independently confirming our results." (PMID 30952872, 2019). "In this study, we investigate a transcription factor of the ETS-family, ETV5, as a putative effector of FGFR3 signalling in bladder cancer." (PMID 30952872, 2019). "Similarly, these genes were also modulated by ETV5 in the invasive bladder cancer cell line 97-7, but not in the non-invasive FGFR3-mutant cell lines, MGHU3 and UMUC14." (PMID 30952872, 2019). "This is not surprising as we have shown that ETV5 expression is modulated by MAPK/ERK signalling, which is a point of convergence of many signalling pathways altered in bladder cancer, such as PI3K, EGFR, and RAS." (PMID 30952872, 2019).
COVID-19 (4 papers, 2023 to 2024). A disease caused by infection with severe acute respiratory syndrome coronavirus 2. "The miRNA 756 target gene ETV5 plays an important role in maintaining lung homoeostasis, and its activity has been found to be reduced in COVID-19 patients." (PMID 36644780, 2023). "Here we characterize the role of ACE2, AR, MX1, ERG, ETV5 and TMPRSS2 for trying a better classification of COVID-19 through knowledge of the disease mechanisms." (PMID 37287057, 2023). "ETV5, which is a transcription factor required for AT2 cell identity, was found to be less expressed in COVID-19 AT2 cells." (PMID 37243274, 2023). "Here we focus on TMPRSS2, and related genes ACE2, MX1, AR, ETV5 and ERG, by its own or combined with clinical data, as an easy and relevant classifier of COVID-19 aggressiveness." (PMID 37287057, 2023).
gastric cancer (4 papers, 2017 to 2025). A primary or metastatic malignant neoplasm involving the stomach. "ETS family members with the highest protein level of expression in many gastric cancer samples include ETV5, ETV4 and ETV3, while ELF2 and ELF3 had moderate to high levels of expression in all samples tested in the Human Protein Atlas but only in one of the two antibodies checked for each protein." (PMID 41425714, 2025). "In gastric cancer, the level of ETV4 mRNA correlated significantly with tumor invasiveness and recurrence, while ETV1 and ETV5 expression were not related to survival." (PMID 29371979, 2017).
glioblastoma (4 papers, 2021 to 2025). The most malignant astrocytic tumor (WHO grade IV). "Analysis of the ceRNA regulatory network associated with ETV5 indicated that ETV5 is regulated by miR-8067 in glioblastoma." (PMID 36872348, 2023). "In glioblastoma, low expression of ETV5 in tumor samples is associated with longer overall survival, which suggested that high expression of ETV5 might be a risk factor for glioblastoma." (PMID 36872348, 2023). "In glioblastoma, knock-down of CIC resulted in ETV5 upregulation, which was consist with the roles of CIC in the suppression of ETV5." (PMID 36872348, 2023). "Moreover, in glioblastoma, the binding of insulin-like growth factor-binding protein 5 (IGFBP5) to ROR1 facilitates the formation of a ROR1/HER2 heterodimer, which subsequently induces the expression of genes like ETV5 and FBXW9 to promote glioblastoma stem-like cell invasion and tumorigenesis." (PMID 40869147, 2025).
thyroid cancer (4 papers, 2021 to 2023). "In thyroid cancer, ETV5 promoted the mesenchymal morphology of cancer cells by regulating the mRNA levels of twist family BHLH transcription factors 1 (TWIST1) and snail family transcriptional repressors 1 (SNAI1)." (PMID 36872348, 2023). "Conversely, factors such as ETS1 and ETV5 showed high and consistent expression across thyroid cancer types, whereas most ETS proteins, including GABPA, were expressed at intermediate levels." (PMID 35053525, 2022). "In thyroid cancer cells, 17b-estradiol increased cell viability and ETV5 expression." (PMID 36872348, 2023).
cleft palate (3 papers, 2009 to 2021). Cleft palate is a fissure type embryopathy that affects the soft and hard palate to varying degrees. "Mice carrying a large deletion of chromosome 14 (Pub36-/-), a region that contains the Spry2 gene exhibit cleft palate, excessive cell proliferation and up regulation of FGF target genes including Msx1, Etv5 and Barx1." (PMID 20459789, 2010). "The link between ETV5, SPRY2 and members of the FGF family offers an exciting opportunity to further explore these interacting developmental pathways in the pathogenesis of cleft palate." (PMID 19401770, 2009).
diabetes (3 papers, 2020 to 2023). "Previous GWASs have shown that genetic variation of ETV5 is predictive of BMI in multiple populations including the Europeans while IGF2BP2 predictive of the onset of diabetes in European populations and a Chinese Han population." (PMID 32366963, 2020). "In region chr3:185324933-186022133, there may exist two independent causal SNPs: rs9816226 (nearest gene: ETV5) for BMI and rs1470580 (in IGF2BP2) for diabetes." (PMID 32366963, 2020).
esophageal squamous cell carcinoma (3 papers, 2022 to 2023). Esophageal squamous cell carcinoma (ESCC) is a type of esophageal carcinoma (EC) that can affect any part of the esophagus, but is usually located in the upper or middle third. "However, no one reported the mechanism behind the association between ETV5 expression and esophageal squamous cell carcinoma progression." (PMID 35813298, 2022). "Knockdown of ETV5 or its downstream genes SKA1 and TRPV2 significantly suppress Esophageal squamous cell carcinoma cells migration and invasion, respectively." (PMID 36052230, 2022). "TAOK3 can augment autophagy and chemo‐resistance in esophageal squamous cell carcinoma (ESCC) cells mechanically by phosphorylating KMT2C and promoting the interaction between KMT2C and ETV5." (PMID 37705061, 2023).
Glucose intolerance (3 papers, 2021 to 2023). Glucose intolerance (GI) can be defined as dysglycemia that comprises both prediabetes and diabetes. "Elevated ETV5 levels impair insulin secretion and lead to glucose intolerance, indicating the key role of the CRL4COP1/DET1-ETV5 axis in nutrient-induced insulin secretion (upper)." (PMID 36872348, 2023). "Etv5-knockout mice present impaired insulin secretion, which results in severe glucose intolerance and insulin resistance." (PMID 34716308, 2021). "Our work suggests that glucose intolerance and insulin resistance in Etv5-knockout mice may also be attributed to the excessive activation of ATMs." (PMID 34716308, 2021).
Insulin resistance (3 papers, 2016 to 2021). Increased resistance towards insulin, that is, diminished effectiveness of insulin in reducing blood glucose levels. "ETV5 modulates circulating glucocorticoids levels and GNPDA2 regulates metabolic pathways leading to insulin resistance." (PMID 27788139, 2016). "PPAR-γ has been reported to control ATM alternative activation and improve insulin resistance, but its expression did not change after Etv5 silencing, indicating that there are other pathways regulated by ETV5." (PMID 34716308, 2021).
liver cancer (3 papers, 2020 to 2024). An epithelial or non-epithelial malignant neoplasm that arises from the liver. "YTHDF2 can also promote immune evasion and angiogenesis in liver cancer by recognizing the m6A modification site in the 5’UTR of ETS variant transcription factor 5 mRNA and recruiting the eukaryotic translation initiation factor 3 subunit B to facilitate its translation." (PMID 39593172, 2024). "As an oncogenic transcription factor, ETV5 has been reported to be an independent predictor of the prognosis of patients with liver cancer." (PMID 34736492, 2021).
lung adenocarcinoma (3 papers, 2019 to 2022). A carcinoma that arises from the lung and is characterized by the presence of malignant glandular epithelial cells. "Additionally, protein levels of ETV5, a key player in the maintenance of Ras-induced lung adenocarcinoma in alveolar type II cells, were higher in HEK293T cells expressing METΔexon14 compared to just ectopic MET WT overexpression." (PMID 35326531, 2022). "(b) Heat map of the PEA3 family ETS transcription factors (ETV1, ETV4, and ETV5) and neuroendocrine transcription factors (ASCL1, NEUROD1, INSM1, and POU3F2 [BRN2]) in small cell lung cancer and lung adenocarcinoma cell lines." (PMID 34121659, 2021).
neuroblastoma (3 papers, 2008 to 2024). Neuroblastoma (NB) is the most common solid, extracranial childhood tumor. "Finally, we established a gene signature associated with ETV5 knockdown, which correlates with poor overall survival in patients with neuroblastoma." (PMID 31937834, 2020). "In neuroblastoma, ETV5 drives tumor aggressiveness through transcriptional regulation mediated by activated ALK mutations and is influenced by the MAPK signaling pathway, a mechanism consistent across different cancer types." (PMID 38515748, 2024). "ETV5 knockdown in vitro and in vivo impaired migration, invasion and proliferation of neuroblastoma cells." (PMID 31937834, 2020). "We demonstrate that elevated ETV5 contributes to migration, clonogenic potential and invasive properties of human neuroblastoma cells while ETV5 knockdown in a xenograft model attenuates proliferation and tumour growth." (PMID 31937834, 2020). "In ALK-activating neuroblastoma cellular backgrounds, the effects of ETV5 reduction on MEK inhibition were significant, albeit attenuated when compared to the same cell lines treated with ALK inhibitor." (PMID 31937834, 2020). "Our findings thus point towards a MAPK pathway-dependent ALK-driven regulation of ETV5 in neuroblastoma." (PMID 31937834, 2020). "This is further in keeping with the ETV5-driven gene signature established in this study which also correlated with poor survival in patients with neuroblastoma." (PMID 31937834, 2020). "Our findings that ETV5 knockdown impaired neuroblastoma cell migration and invasive capacity are in line with these findings in multiple tumour entities." (PMID 31937834, 2020). "The precise molecular principle by which ETV5 impairs neuroblastoma cell migration and invasion remains, however, to be elucidated." (PMID 31937834, 2020). "At present, we can only speculate on a potential role for ETV5 in trametinib resistance in ALK-activated neuroblastoma." (PMID 31937834, 2020). "To investigate the impact of the ETV5 transcription factor on the neuroblastoma cell transcriptome in relation to the observed phenotypic effects, we performed gene expression profiling after stable ETV5 knockdown in SH-SY5Y cells in vitro and in vivo after subcutaneous xenografting." (PMID 31937834, 2020). "To evaluate the functional impact of ETV5 levels in neuroblastoma cells with different mutant ALK backgrounds, we performed transient (siRNA) and stable (shRNA) ETV5 knockdown in CLB-GA (ALKR1275Q), NB-1 (ALKamp), SK-N-AS (ALKwt, NRASQ61K), and SH-SY5Y (ALKF1174L) cells." (PMID 31937834, 2020). "To evaluate through which ALK downstream signalling axis ETV5 is regulated in neuroblastoma cells, we treated CLB-GA (ALKR1275Q), NB-1 (ALKamp), SK-N-AS (ALKwt, NRASQ61K) and SH-SY5Y (ALKF1174L) cells with inhibitors for the two major pathways downstream of ALK." (PMID 31937834, 2020). "By exposing neuroblastoma cells to MAPK and PI3K/AKT inhibitors, we confirmed that ALK signals through the MAPK pathway to control ETV5 levels." (PMID 31937834, 2020). "After our extensive validation of ETV5 regulation by ALK and RAS/MAPK signalling in neuroblastoma cells, we investigated the contribution of ETV5 to the neuroblastoma cellular phenotype." (PMID 31937834, 2020). "Here, ETV5 expression was significantly elevated in ALKmut neuroblastomas compared to tumours harbouring ALKwt or lacking ALK amplifications." (PMID 31937834, 2020). "Taken together, our data highlight ETV5 as an intrinsic component of oncogenic ALK-driven signalling through the MAPK axis and propose that ETV5 upregulation in neuroblastoma may contribute to tumour aggressiveness." (PMID 31937834, 2020).
oligodendroglioma (3 papers, 2019 to 2023). A well-differentiated (WHO grade II), diffusely infiltrating neuroglial tumor, typically located in the cerebral hemispheres. "The CIC-double homeobox 4 (DUX4) fusion oncoprotein retains CIC DNA-binding specificity but gains activating capacity to increase ETV5 transcription, which is consistent with the overexpression of ETV5 in CIC-mutant oligodendrogliomas." (PMID 36872348, 2023). "In patient-derived oligodendroglioma cells, CIC re-expression or ETV5 blockade decreases lineage bias, proliferation, self-renewal, and tumorigenicity." (PMID 31043608, 2019). "RNAseq data from TCGA identified 221 differentially expressed genes in CIC mutant versus wild-type oligodendrogliomas (fold cutoff of 1.5, p-value < 0.05 and FDR < 10%) amongst which the known CIC targets ETV1, ETV4, and ETV5 were significantly up-regulated in CIC-mutant cases." (PMID 30737375, 2019).
papillary thyroid cancer (3 papers, 2021 to 2023). "In papillary thyroid cancers the ETS variant 5 (ETV5) is abundantly expressed and able to activate mutant TERT promoter in GABP-negative thyroid cancer cells." (PMID 38033865, 2023). "Additionally, in papillary thyroid cancer model, silencing of ETV5 causes a decrease in cell proliferation and this was associated with a diminished expression of CCND1 (cyclin D1) and CCND2 (cyclin D2)." (PMID 37876309, 2023). "In papillary thyroid carcinoma, ETV5 is highly expressed and can promote the expression of the twist-related protein 1 (TWIST1) gene, which has been shown to induce the EMT process." (PMID 34736492, 2021). "In papillary thyroid carcinoma, ETV5 is upregulated and may be involved in its epithelial–mesenchymal transition (EMT)." (PMID 34736492, 2021).
sarcoma (3 papers, 2015 to 2022). A usually aggressive malignant neoplasm of the soft tissue or bone. "Moreover, several sarcoma-associated gene mutations were found, including AR mutation (p.G473del, 11.11%), AXL mutation (p.T45P, 8.11%), and ETV5 mutation (p.F11Y, 33.33%)." (PMID 36153506, 2022). "Moreover, CIC-DUX4 sarcomas are characterised by consistent ETV1, ETV4, and ETV5 upregulation, and ETV4 immunohistochemistry has been identified as a highly sensitive marker for this tumour entity." (PMID 28680140, 2017).
allergic disease (2 papers, 2018 to 2024). An immune response that occurs following re-exposure to an innocuous antigen, and that requires the presence of existing antibodies against that antigen. "Immune-related diseases, including cancer, allergies, autoimmune diseases, and atherosclerosis, are often associated with abnormal expression of PU.1 and ETV5." (PMID 39337492, 2024).
autoimmune disease (2 papers, 2017 to 2024). A disorder resulting from loss of function or tissue destruction of an organ or multiple organs, arising from humoral or cellular immune responses of the individual to their own tissue constituents. "In this regard, CIC and ETV5 themselves or their target genes that commonly mediate pathogenesis of both diseases could be evaluated as molecular targets for treatment of both autoimmune diseases and cancers." (PMID 28855737, 2017).
breast tumors (2 papers, 2010 to 2016). "Although overexpression of PEA3 (E1AF/ETV4), and of the related factors ERM (ETV5) and ER81 (ETV1), have been observed in human and mouse breast tumors, PEA3 factors have also been ascribed a tumor suppressor function." (PMID 20107508, 2010).
chondrosarcoma (2 papers, 2023 to 2025). A malignant cartilaginous matrix-producing mesenchymal neoplasm arising from the bone and soft tissue. "It has been shown that the restoration of miR-145 expression by lentiviral transfection results in the downregulation of SOX9, ETV5, and MMP-2, leading to the reduced invasion and metastasis of Chondrosarcoma cells." (PMID 40429954, 2025). "In Chondrosarcoma, low levels of miR-145 lead to the overexpression of SOX9, which in turn activates ETV5, a transcription factor involved in metastasis, ultimately leading to the increased expression of MMP-2 and increased extracellular matrix degradation." (PMID 40429954, 2025). "In chondrosarcoma, SOX9 enhances ETV5 promoter activity when co-transfect ETV5 promoter-reporter plasmid with SOX9 overexpressing lentivirus, but the specific binding sites and interaction mechanism remain to be determined." (PMID 36872348, 2023).
Ewing sarcoma (2 papers, 2016 to 2021). A small round cell tumor that lacks morphologic, immunohistochemical, and electron microscopic evidence of neuroectodermal differentiation. "The ERG related members include ETV1, ETV4, ETV5 and FLI1 which have been shown to overexpress in different diseases including CaP, Ewing sarcoma, and acute myeloid leukemia." (PMID 28191285, 2016).
Hepatic steatosis (2 papers, 2021 to 2024). Steatosis is a term used to denote lipid accumulation within hepatocytes. "Therefore, Etv5 may play an important role in JQF’s regulation of Th2 cells in hepatic steatosis and inflammation associated with NAFLD." (PMID 39840059, 2024).
male infertility (2 papers, 2017 to 2021). The inability of the male to effect fertilization of an ovum after a specified period of unprotected intercourse. "In human and mouse male infertility, we observed the highest similarity between Etv5 and Pou3f1 KD in the up-regulated gene lists." (PMID 29150651, 2017).
oligospermia (2 papers, 2017 to 2018). Decreased number of spermatozoa in the semen. "ZIKV infection leads to several testicular pathologies, including involution of the SNT, degeneration of spermatogenic cells, oligospermia, a high proportion of sperm with abnormal morphology, poor expression of TRA98 and ETV5." (PMID 29447264, 2018).
oral squamous cell carcinoma (2 papers, 2021 to 2022). "HGF upregulates ETV5 to promote cell invasion of oral squamous cell carcinoma." (PMID 36109787, 2022).
ovarian tumor (2 papers, 2011 to 2025). "The transcription factor ETV5 is significantly upregulated in ovarian tumor samples and transcriptionally activates FOXM1." (PMID 40746724, 2025). "Moreover, increased ETV5 expression correlates with elevated FOXM1 transcript levels in ovarian tumor samples." (PMID 40746724, 2025).
rectal adenocarcinoma (2 papers, 2021 to 2022). "Furthermore, we found a significantly higher expression of ETV4 and ETV5 in cancer tissues of both colon adenocarcinoma (COAD) and rectal adenocarcinoma (READ) via TIMER." (PMID 35860243, 2022).